LAMP3 (lysosome associated membrane protein 3)
Diseases named in the same sentence as LAMP3 in open-access papers (continued):
Sharing a sentence is not in itself a finding about the gene and the disease.
asthma (4 papers, 2013 to 2025). "Further, a study observed that Sftpc, Nxnl, Lamp3, Gpr 171, and Cox14 genes is associated with asthma and the association is even stronger with atopic and severe asthma." (PMID 40313552, 2025). "In summary, the lipid homeostasis for surfactant production in BAL of Lamp3-/- mice was more disturbed under the pathophysiologic conditions of experimental asthma when compared to the unchallenged animals." (PMID 34161347, 2021). "The response to experimentally induced asthma led to further divergence in the BAL lipid composition between Lamp3-/- mice and wildtype." (PMID 34161347, 2021). "We observed that the mild, moderate, and severe asthma subject in the extreme low temperature group showed increased Tob1, Mub2, Sic34a2, Sftpc, Nxnl, Luc71, Lamp3, Gpr171, Cox14, and Cd3e expression, while in the severe asthma subjects showed increased expression in all temperature exposure group." (PMID 40313552, 2025). "Additionally, subjects with severe asthma were more sensitive to low, high temperature and temperature fluctuation conditions, with increased of Tob1, Mub2, Sic34a2, Sftpc, Nxnl, Luc71, Lamp3, Gpr171, Cox14, and Cd3e expression." (PMID 40313552, 2025). "The two different conditions genotype (wildtype/ LAMP3-KO) and challenge (none/ allergen induced asthma) resulted in four groups of mice." (PMID 40233092, 2025).
endometrial cancer (4 papers, 2023 to 2025). Primary or metastatic malignant neoplasm involving the endometrium (mucous membrane that lines the endometrial cavity). "The overexpression rates of PD-1 (CD279) and PD-L1 (CD274) in endometrial cancer have been reported to be the highest of all gynaecological cancers, so we evaluated LAMP3 expression levels and the correlation of multiple immune checkpoints in detail." (PMID 38217544, 2024). "Furthermore, the ability of LAMP3 to recruit Treg cells in bladder cancer and participate in the formation of an immunosuppressive microenvironment drove us to deepen our exploration of the specific immunological functions of LAMP3 in endometrial cancer." (PMID 38217544, 2024). "However, the role of LAMP3 in endometrial cancer has been overlooked by previous researchers." (PMID 38217544, 2024). "Amplification of LAMP3 mRNA was found in many tumours including BLCA, BRCA, CESC, endometrial cancer, ESCA, HNSC, NSCLC and OV." (PMID 38146591, 2024). "Most LAMP3 genetic alterations were mainly detected in NSCLC, OV, HNSC, CESC, ESCA and endometrial cancer." (PMID 38146591, 2024). "Within this research, we screened for LAMP3 by the WGCNA approach in combination with gene characterisation and explored the differential expression of LAMP3 in endometrial cancer and normal tissues, the relationship with clinicopathological features, and the mechanisms of expression regulation." (PMID 38217544, 2024).
esophageal cancer (4 papers, 2020 to 2024). A primary or metastatic malignant neoplasm involving the esophagus. "Furthermore, by triggering regional PKA expression and encouraging VASP phosphorylation at Ser239, the deletion of LAMP3 significantly reduced the motility and spread of esophageal cancer cells." (PMID 38922530, 2024). "Besides, molecules, like Caveolin-1, Ezrin, and LAMP3, were also checked in esophageal carcinoma tissues." (PMID 34178655, 2021).
lymph node metastasis (4 papers, 2014 to 2024). "High expression of LAMP3 was significantly associated with T stage (p = 0.002) and lymph node metastasis (p = 0.002)." (PMID 39429383, 2024). "High LAMP3 expression and its significant association with TNM stage, T stage, and lymph node metastasis suggest a major role for LAMP3 in OSCC progression." (PMID 39429383, 2024). "High LAMP3 expression and its significant association with TNM stage, T stage, and lymph node metastasis suggest a potential role for LAMP3 in OSCC carcinogenesis." (PMID 39429383, 2024). "In this study, high LAMP3 expression was significantly linked to T stage and lymph node metastasis." (PMID 39429383, 2024). "Numerous studies have reported a significant relationship between LAMP3 and lymph node metastasis." (PMID 39429383, 2024). "In our study, high expression of LAMP3 was more frequent at the primary sites of patients with lymph node metastasis than in those without metastasis (56.2% vs. 44.1%), although not statistically significant, which might due to the small sample size (50 vs. 30)." (PMID 26263981, 2015).
Parkinson disease (4 papers, 2012 to 2025). A progressive degenerative disorder of the central nervous system characterized by loss of dopamine producing neurons in the substantia nigra and the presence of Lewy bodies in the substantia nigra and locus coeruleus. "For example, a case-control study of 1428 Han Chinese reported that the allele of MCCC1/LAMP3 (rs11711441) polymorphism is linked to a lower risk of Parkinson’s disease." (PMID 40170191, 2025). "Examples include GIPR–caffeine interaction and obesity and include LAMP3–selenium interaction and Parkinson disease." (PMID 27934696, 2016).
Autoimmunity (3 papers, 2013 to 2022). The occurrence of an immune reaction against the organism's own cells or tissues. "Our data from the LAMP3 overexpression mouse suggests that the lysosomal changes in SGECs could be responsible for the initiation of autoimmunity." (PMID 33658234, 2021). "Taken together, the bioinformatics analysis supports a hypothesis that LAMP3 expression in SGECs can be stimulatory to monocytes/macrophages as an initiator of autoimmunity." (PMID 33658234, 2021). "The newly identified LAMP3/HSP70/BMP6 axis provided an etiological model for SS gland dysfunction and autoimmunity." (PMID 35113815, 2022).
gastric tumor (3 papers, 2022 to 2024). "Next, trajectory analysis of these three subsets revealed that LAMP3+ DCs potentially were developed from cDC2 and cDC1 in gastric tumors." (PMID 35664061, 2022). "To explore the origin of LAMP3+ DCs in gastric tumors, we first built a dendrogram of myeloid clusters and found that LAMP3+ DCs were clustered with cDC1 and cDC2." (PMID 35664061, 2022). "Furthermore, the average expression of signature genes for LAMP3+ DCs was also much higher in the stomach tumor samples in TCGA dataset." (PMID 35664061, 2022).
laryngeal squamous cell carcinoma (3 papers, 2017 to 2024). A squamous cell carcinoma that arises from the larynx.
non-alcoholic fatty liver disease (3 papers, 2022 to 2024). "LAMP3 is elevated in obese mice and associated with the progression of non-alcoholic fatty liver disease (NAFLD), while CEASAM6 is elevated in Crohn disease patients and may be an index of colon inflammation." (PMID 36437471, 2022). "For instance, in nonalcoholic fatty liver disease (NAFLD), the overexpression of LAMP3 substantially increased the lipid accumulation of hepatocytes, in our study, we also found that the expression of LAMP3 in the liver of NASH patients was significantly higher than that in healthy controls." (PMID 37006307, 2023).
atopic dermatitis (2 papers, 2022 to 2023). "Recently, researchers have identified a small subset of skin DCs called mregDCs with high expressions of BIRC3, LAMP3, IL15, CD40, and CCR7, and this subset has been thought to be associated with wound healing and the exacerbation of atopic dermatitis." (PMID 35280984, 2022).
colon cancer (2 papers, 2014 to 2024).
head and neck cancer (2 papers, 2017 to 2024). A primary or metastatic malignant neoplasm affecting the head and neck. "As shown, NNMT, FLI1, SLPI, LAMP3, SERPINA1, GAS6, and CD274 have been often used as biomarkers for OSCC or head and neck cancer, while other genes listed have seldom been investigated in oral cancer and may be considered as novel biomarkers for OSCC prevalence and treatment." (PMID 28286742, 2017).
interstitial lung disease (2 papers, 2020 to 2021). A diverse group of lung diseases that affect the lung parenchyma. "Our study suggests that in unresolved cases of interstitial lung disease in neonatal babies, variants in LAMP3 should be closer investigated." (PMID 32150563, 2020). "In conclusion, we have characterized a neonatal interstitial lung disease in a dog breed with a missense variant in AECII cell LB limiting membrane protein LAMP3." (PMID 32150563, 2020). "Notably, a naturally occurring recessive missense LAMP3 variant has recently been associated with a fatal neonatal interstitial lung disease in Airedale Terrier dogs." (PMID 34161347, 2021). "In summary, this study describes a novel interstitial lung disease in dogs, identifies a new candidate gene for human surfactant dysfunction and brings important insights into the essential role of LAMP3 in the process of the LB formation." (PMID 32150563, 2020).
liver cancer (2 papers, 2020 to 2022). An epithelial or non-epithelial malignant neoplasm that arises from the liver. "Primarily, LAMP3 was reported in lung tissues but is found to have overexpression in multiple primary cancers, including breast, lung, and liver cancers." (PMID 36139498, 2022). "Interestingly, we found that LAMP3 + DC had multiple functions, such as activation activity, migration activity, and tolerogenic ability, and this subset was also found and reported in lung and liver cancers, suggesting the conserved myeloid cells exist in many tumors." (PMID 33293583, 2020).
metastatic melanoma (2 papers, 2023). A melanoma that has spread from its primary site to another anatomic site. "As for the immunomodulatory mechanism of SNTB2, SLC1A4, LAMP3 and CCDC69 in metastatic melanoma or macrophages, it was not specifically elucidated, though it is still a promising research direction." (PMID 37762054, 2023).
nasopharyngeal carcinoma (2 papers, 2024 to 2025). A carcinoma arising from the nasopharyngeal epithelium. "In nasopharyngeal carcinoma (NPC) the infiltration of LAMP3+cDCs in tumors is significantly increased than in normal tissues." (PMID 40491907, 2025).
non-small cell lung carcinoma (2 papers, 2018 to 2023). A group of at least three distinct histological types of lung cancer, including non-small cell squamous cell carcinoma, adenocarcinoma, and large cell carcinoma. "In patients with IIIA non-small cell lung cancer after neoadjuvant pembrolizumab and chemotherapy, LAMP3+ DCs involved in the process of lymphocytes recruitment and regulation, its increased levels were found to be associated with positive clinical outcomes by single-cell profiling." (PMID 37082269, 2023).
oral squamous cell carcinoma (2 papers, 2017 to 2024). "Relationship of LAMP3 expression with clinicopathological parameters in oral squamous cell carcinoma." (PMID 39429383, 2024). "However, the expression of LAMP3 and its value in oral squamous cell carcinoma (OSCC) remain unclear." (PMID 28607528, 2017).
pancreatic adenocarcinoma (2 papers, 2022 to 2023). "In pancreatic adenocarcinoma, urothelial bladder carcinoma, and cutaneous T-cell lymphoma, LAMP3+ DCs also promote immune tolerance and immunosuppression through interacting with CD8+T or tumor-infiltrating Tregs." (PMID 37006307, 2023). "A recent study revealed that LAMP3+ DCs in pancreatic adenocarcinoma might promote immune tolerance through interacting with tumor-infiltrating Tregs, supporting our conclusions." (PMID 36357424, 2022).
pancreatic cancer (2 papers, 2020 to 2022). "LAMP3 has not been previously studied in relation to pancreatic cancer, but lysosome-associated membrane proteins are involved in autophagy and have been proposed to have functions in tumour progression and metastatic spread." (PMID 35064782, 2022).
respiratory failure (2 papers, 2021). The significant impairment of gas exchange within the lungs resulting in hypoxia, hypercarbia, or both, to the extent that organ tissue perfusion is severely compromised. "Respiratory failure was signified by depression of EGF, GZMA, LAP, IL-4, and IL-7, and increased expression of MUC-16, ARG-1, and LAMP-3." (PMID 34177897, 2021). "Patients requiring respiratory failure showed depressed CD27, CXCL1, CXCL13, Gal-1, Gal-9, HO-1, IL-18, LAMP3, MCP-3, TNFRS12A." (PMID 34608231, 2021).
type I diabetes (2 papers, 2021 to 2024). "Meanwhile, LAMP3 was related to biological processes including necroptosis, cell adhesion, type I diabetes mellitus and NOD‐like receptor signalling pathway." (PMID 38146591, 2024). "Meanwhile, LAMP3 was associated with biological processes such as necroptosis in CESC, OV, UCEC, cell adhesion in BRCA, KIRC, LUAD, LUSC, SKCM and type I diabetes mellitus in BRCA, HNSC and LUAD." (PMID 38146591, 2024).
adenocarcinoma in situ (1 paper, 2019). A lesion in which the normally situated glands are partially or completely replaced by atypical cells with malignant characteristics. "LAMP3 has previously been detected in OPA but is rarely expressed in human tumors, except in bronchioloalveolar adenocarcinoma (lepidic-prominent adenocarcinoma in situ), which was not represented in the LUAD cases in the TGCA data studied." (PMID 31434729, 2019).
AIDS (1 paper, 2022). A syndrome resulting from the acquired deficiency of cellular immunity caused by the human immunodeficiency virus (HIV). "In addition, our study also indicated a putative role for novel mediators of HIV-1 immunity, namely ZBP1, LAMP3, CXCL10, LGALS9, and ANKYF1, all of which have been associated with HIV-1/AIDS disease progression." (PMID 35333911, 2022).
allergic asthma (1 paper, 2021). A asthma with a basis in a pathological type I hypersensitivity reaction. "In ovalbumin-induced experimental allergic asthma, the changes in lipid composition are aggravated, and LAMP3-deficient mice exert an increased airway resistance." (PMID 34161347, 2021). "However, under diseased conditions of experimental allergic asthma, changes in the lipid composition are aggravated and are associated with an impaired lung function, suggesting an important role of LAMP3 in the homeostasis of pulmonary surfactant." (PMID 34161347, 2021). "Taken together, whereas the lack of LAMP3 appears to be compensable under physiological conditions, it impacts basal surfactant homeostasis and lung lipid composition and airway resistance in experimental allergic asthma." (PMID 34161347, 2021).
chronic hepatitis B (1 paper, 2023). "The LAMP3 expression in the liver of patients with chronic hepatitis B (CHB) was analyzed in three GEO datasets and confirmed in our validation cohort (27 patients with CHB)." (PMID 37006307, 2023).
clear cell renal cell carcinoma (1 paper, 2025). "In the literature, infiltration of LAMP3+ DC, representing a mature, antigen-presenting DC population, is linked to TLS maturation stages, as early TLS had a significantly lower abundance of LAMP3+ DC than primary or secondary follicle TLS in clear cell renal cell carcinoma." (PMID 40282480, 2025).
dacryoadenitis (1 paper, 2023). Inflammation and enlargement of the lacrimal gland. "Future studies need to clarify if HCQ can ameliorate LAMP3-associated dacryoadenitis." (PMID 36821638, 2023).
dilated cardiomyopathy (1 paper, 2021). Cardiomyopathy which is characterized by dilation and contractile dysfunction of the left and right ventricles. "Moreover, previous studies have also demonstrated that lysosomal associated membrane protein 3 (LAMP3) is expressed in human heart and cardiomyocytes, and that its expression is elevated in dilated cardiomyopathy hearts with severe heart remodeling." (PMID 34753383, 2021).
dyslexia (1 paper, 2022). A learning disorder characterized by an impairment in processing written words. "Consistent with the results from the binding assay, LAMP3 overexpression did not alter expression of dyslexia-associated protein KIAA0319-like protein (KIAA0319L, also named AAV receptor), a protein associated with AAV2 binding." (PMID 36329045, 2022).
liver dysfunction (1 paper, 2023). "Additionally, the increased LAMP3 expression was positively associated with liver dysfunction caused by HBV infection." (PMID 37006307, 2023).
lung adenocarcinoma (1 paper, 2024). A carcinoma that arises from the lung and is characterized by the presence of malignant glandular epithelial cells. "LAMP3 expression has been reported to influence the prognosis of lung adenocarcinoma by regulating the infiltration levels of B cells, dendritic cells, natural killer cells, and eosinophils." (PMID 38217544, 2024).
metastasis (1 paper, 2022). The spread or migration of cancer cells from one part of the body (where they first appeared) to another. "A high LAMP3 protein expression was significantly associated with the migration and invasion of tumor cells in vitro, lymph node metastasis, and poor overall survival." (PMID 35204406, 2022).
osteoarthritis (1 paper, 2020). A noninflammatory degenerative joint disease occurring chiefly in older persons, characterized by degeneration of the articular cartilage, hypertrophy of bone at the margins and changes in the synovial membrane. "LAMP3 was one of the differentially expressed genes between RA and osteoarthritis patients, and CD83 was expressed in more than 20% of pDCs in the RA synovium." (PMID 32164778, 2020).
preeclampsia (1 paper, 2023). Preeclampsia is a hypertensive disorder of pregnancy that is characterized by new-onset hypertension with proteinuria presenting after 20 weeks of gestation, and depending on mild or severe forms may initially present with severe headache, visual disturbances, and hyperreflexia. "Compared with the normal placentas, LAMP3 was highly expressed in CK7-positived cells of preeclampsia placenta." (PMID 37878884, 2023). "Firstly, the mRNA and protein levels of LAMP3 were significantly upregulated in the placentas of preeclampsia patients compared to normal placentas, especially in trophoblast cells (a key component of the human placenta)." (PMID 37878884, 2023). "The objectives of this study were to investigate the role of lysosome-associated membrane glycoprotein 3 (LAMP3) in the pathogenesis of preeclampsia and to evaluate whether vitamin D supplementation would protect against the development of preeclampsia by regulating LAMP3 expression." (PMID 37878884, 2023). "The mRNA and protein levels of LAMP3 in preeclampsia placenta were upregulated compared with normal samples." (PMID 37878884, 2023).
psoriasis vulgaris (1 paper, 2013). Plaque psoriasis is the most common presentation of psoriasis. "LAMP3 appears to be a marker of dendritic cell maturation and has been implicated in the pathogenesis of psoriasis vulgaris." (PMID 24188128, 2013).
pulmonary fibrosis (1 paper, 2021). Chronic progressive interstitial lung disorder characterized by the replacement of the lung tissue by connective tissue, leading to progressive dyspnea, respiratory failure, or right heart failure. "The results showed that in AT-II-associated proteins (LAMP3, ABCA3, and SFTPC), the expression of ABCA3 and SFTPC was significantly downregulated, which can also suggest the loss of AT II in pulmonary fibrosis." (PMID 34645797, 2021).
synucleinopathies (1 paper, 2021). "The specific role of LAMP3 in this pathway and how it may be involved in iRBD and the subsequent synucleinopathies will require additional studies." (PMID 33397775, 2021).